S100A4 (S100 calcium binding protein A4)
Diseases named in the same sentence as S100A4 in open-access papers (continued):
Sharing a sentence is not in itself a finding about the gene and the disease.
cancer (continued). "S100A4 is known to modulate the motility of both non‐transformed and cancer cells by regulating the localization and stability of cellular protrusions." (PMID 26734465, 2015). "This is an important finding since S100A4 has been shown to be an important mediator of cancer cell metastasis and therapeutic targeting of its function is a major strategy being currently developed against cancer." (PMID 26734465, 2015). "The protein S100A4 is best known for its significant role in promoting motility and invasive capacity of cancer cells." (PMID 26734465, 2015). "In this regard, it is interesting to note that the abundance of S100A4 has been positively correlated to the self-renewal capability and stemness of different cancer stem cells by other authors." (PMID 25738360, 2015). "Inhibition of hypoxia-inducible factor-1 by saponin extracts of ginsenoside (Ginsen) and Gynostemma and inhibition of S100A4 by coix polysaccharides inhibited cancer cell migration and invasion." (PMID 25226533, 2014). "Many studies indicated a pathophysiological role for S100A4 in the development of cancer by promoting proliferation, angiogenesis, cell motility and invasiveness." (PMID 25152734, 2014). "The small Ca2+ binding protein S100A4 has been reported to be highly expressed in different cancer tissues." (PMID 24952599, 2014). "Previous studies into the roles of S100A4 have predominantly focused on the invasive growth and metastasis of cancer." (PMID 24944689, 2014). "In the human cancer xenograft model used in this study, only host S100A4 was targeted to explore the role of S100A4 in angiogenesis." (PMID 23929008, 2014). "Several relevant genes such as uPA and S100A4 have altered epigenetic patterning in cancer cells, allowing cell morphology to be modified to a more metastatic-favourable state." (PMID 25079072, 2014). "Interacting with several target proteins, S100A4 affects a number of activities, accelerating tumorigenesis and invasion of human cancers." (PMID 25359220, 2014). "S100a4, a member of the S100 family of calcium-binding proteins, has been shown to activate pathways characteristic of cancer metastasis." (PMID 24465393, 2014). "It is concluded that extracellular S100A4 inhibition is an attractive approach for the treatment of human cancer." (PMID 24023743, 2013). "Via its direct interaction with NF-κB, S100A4 is also reputed to be involved in cancer cell proliferation and differentiation." (PMID 23469180, 2013). "To date, S100A4 has been mainly known as a cancer metastasis gene and its expression has been shown to promote cancer metastasis by inducing angiogenesis and disruption of the extracellular matrix." (PMID 23922901, 2013). "Clinical evidence has also indicated a correlation between S100A4 overexpression and prognosis in several cancer types, such as bladder cancer, breast cancer, esophageal-squamous cancer, gastric cancer, lung cancer, and pancreatic cancer." (PMID 24188373, 2013). "A number of functions have been attributed to S100A4, including effects on cell motility, cytoskeletal rearrangements, signaling cascades, cancer progression, apoptosis, and cellular differentiation." (PMID 23028424, 2012). "In turn, genomic knock-out of S100A4 strongly decreased the metastasis formation of highly metastasizing cancer cells in mice." (PMID 22878175, 2012). "Positive immunohistochemical staining for VIM and S100A4 in cancer cells was observed in the cytoplasm, and a combination of the nucleus and cytoplasm." (PMID 22761930, 2012). "S100A4 is regarded as a mediator of metastasis and studies on patients have shown a correlation between S100A4 upregulation and poor prognosis in cancer." (PMID 22279561, 2012). "Combining MACC1 with circulating transcripts of the metastasis gene S100A4, a transcriptional target of the Wnt/β-catenin-pathway, improves survival prediction for newly diagnosed cancer patients." (PMID 23166620, 2012).
cancer (continued). "Simultaneously, CM from cancer cells upregulated S100A4 expression, which is known to be overexpressed in activated fibroblasts and HMF3s fibroblasts, and stimulated substantial elongation of fibroblasts." (PMID 20723242, 2010). "Overexpression of S100A4 is more frequently found in cancer cells than in normal colonic mucosa, as well as more in liver metastasis than in primary tumors." (PMID 20515499, 2010). "The murine S100A4 concentration in TIFs from mice injected with cancer cells alone ranged from 39.4 to 60.3 ng/ml (mean, 51.5 ± 12.2 ng/ml)." (PMID 20723242, 2010). "At least 50 genes in our list are already known to be regulated by DNA methylation, such as those encoding cancer antigens (a set of MAGE and GAGE), H19, S100A4, IGFBP4, UCHL1, COL1A2, CLU, FN1, and TGFBI." (PMID 19234609, 2009). "Induction of optineurin gene expression by metastasis promoting protein S100A4 and the regulation of optineurin promoter by NF-κB provide a basis for exploring the role of optineurin in cancer development." (PMID 19340308, 2009). "When S100A4 was immunoprecipitated from these normal cells and analyzed by 2D-PAGE the same distribution as described for S100A4 isolated from cancer cells was observed." (PMID 18554396, 2008). "This suggests that S100A4 is highly expressed in newly growing cancer either in the primary or metastatic sites." (PMID 18771601, 2008). "An increase in S100A4 protein expression has been correlated with a worse prognosis for patients with different types of cancer including colorectal, gallbladder, bladder, esophageal, breast, and non small lung cancer." (PMID 18771601, 2008). "In line with this, increased expression of S100A4 has been correlated with adverse prognosis in patients with various types of cancer." (PMID 18554396, 2008). "S100A4 is a member of small calcium-binding protein family and is involved in the cell proliferation and cancer progression." (PMID 16265347, 2005). "This staining together with immunocytochemical staining of such specimens, localized the S100A4 mRNA/protein to clusters of small cells in the cancer specimen, which had the histological appearance of lymphocytes." (PMID 11875708, 2002). "These paired specimens of primary carcinoma and secondary liver metastases exhibited mean values of S100A4 mRNA of 22.7%±s.e." (PMID 11875708, 2002). "The presence of S100A4 in the carcinoma cells in the liver was confirmed by immunocytochemical staining with an antibody to S100A4." (PMID 11875708, 2002). "In situ hybridization and immunocytochemistry techniques have localized S100A4 to both carcinoma cells and lymphocytes in the malignant specimens." (PMID 11875708, 2002). "Using immunocytochemistry, these results are broadly confirmed, the proportion of specimens with epithelial cells staining for S100A4 increases successively between normal tissue, carcinoma and liver metastases." (PMID 11875708, 2002). "S100A4 can also promote cancer metastasis by enhancing premetastatic niche formation." (PMID 40078995, 2025). "NF-κB, a transcription factor known for its role in promoting cancer cell survival and invasion, was found to be significantly activated upon S100A4 stimulation in this study, which demonstrated that NF-κB inhibition via Bay-11-7082 rescues hsa-miR-125b-5p expression, thereby reducing MMP-2 levels." (PMID 41155277, 2025). "S100A4 is expressed in T cells during lineage commitment and memory differentiation, as well as in pathological conditions of asthma, arthritis, chronic infection, and cancer." (PMID 40078995, 2025). "These indicate that membrane SFPQ/S100A4 affects cell invasion in cancer cells." (PMID 40770831, 2025). "Importantly, several biomarkers (such as CX3CR1 and S100A4) were identified and verified to distinguish between responders and non‐responders to immunotherapy in both cancer mouse models and patients with cancer." (PMID 40574416, 2025).
cancer (continued). "However, it is important to also consider that S100A4 is expressed in multiple cell types, including in cancer cells." (PMID 40078995, 2025). "Similarly, PCR detection showed that TGFβI and S100A4 mRNA levels in cancer tissues were (1.79±0.58) and (1.35±0.42) respectively, which were higher compared to adjacent tissues (P<0.05)." (PMID 40821652, 2025). "When fibrosis occurs within the TME in the context of cancer, S100A4 has immunomodulatory effect." (PMID 40078995, 2025). "The S100A4 controls several signalling pathways, including PI3K/AKT and Wnt/β-catenin, which are directly linked to invasion, migration, epithelial-mesenchymal transition (EMT) and resistance in cancer cells." (PMID 40270992, 2025). "S100A4 was initially nominated as a therapeutic target in the context of cancer metastasis." (PMID 40078995, 2025). "Cancer cells treatedwith novel phenylproline inhibitors showed a reduction in cell proliferationand migration, which is very consistent with the inhibition of S100A4-NMIIinteractions and its downstream signaling." (PMID 39425667, 2024). "Therefore, S100A4 contributes to the functional liaison between cancer cells and the surrounding microenvironment to ward worse outcome." (PMID 39830522, 2024). "Notably, calcium‐blinding protein S100A4 released from cancer cells is critical to drive osteolysis." (PMID 39415352, 2024). "For a long time, S100A4 was considered to only play an important function in cancer." (PMID 39766257, 2024). "S100A4 is a well-known promoter of cancer cell migration, invasion and metastasis." (PMID 39361615, 2024). "Thus, dying cancer cells have a beneficial effect on nearby live cancer cells through an unreported chromatin-bound S100a4." (PMID 36973439, 2023). "Besides AGEs and HMGB1, S100 group of proteins like S100A4 and S100A7 are also implicated in cancer growth, migration and angiogenesis via potent interaction with RAGE and potential re-modelling of tumour micro-milieu." (PMID 37970208, 2023). "This second cluster could represent a cancer-associated fibroblast (CAF) population characterized by low expression of MSLN and WT1 and high expression of ACTA2, S100A4, COL5A2, SPARC, and FN1." (PMID 36901697, 2023). "Additionally, due to the activation of receptor tyrosine kinase (c-MET), the infiltration of neutrophils by S100A4 and increased expression of invasion-promoting integrin β1 in cancer cells is observed." (PMID 37569531, 2023). "In addition to its role in cancer metastasis, S100A4 is also reported in various pathophysiologies such as inflammation, fibrosis, angiogenesis, and neuroprotection." (PMID 35965620, 2022). "Moreover, the transfection of S100A4-specific small interfering RNA significantly reduced S100A4 protein expression, concomitantly lowering the migratory and invasion ability in the HeLa and SiHa cancer cells." (PMID 35214097, 2022). "Furthermore, we identify S100A4 as a regulator of immune suppressive T and myeloid cells in GBM and demonstrate that deleting S100a4 in non-cancer cells is sufficient to reprogram the immune landscape and significantly improve survival." (PMID 35140215, 2022). "Upregulated genes in mEPCs, including IGF2, GPC3, S100A4, STMN1, and MDK, were semi-automatically assigned to the traditional cancer hallmark framework 15, including proliferative signaling, invasion/metastasis, genomic instability, immune response, and stem cell-like program." (PMID 36198671, 2022). "S100A4 exhibits an increased level in various types of cancer." (PMID 35214097, 2022). "S100A4 secreted in cancer tissues may play roles in the acceleration of inflammation, angiogenesis, invasive motility, and fibrosis." (PMID 36142212, 2022). "Our observation, that MACC1 and S100A4 form a signaling axis through β-catenin might add to characterization of molecular cancer subtypes with high metastatic potential and novel intervention points for improved anti-metastatic therapy." (PMID 36008464, 2022).
cancer (continued). "Consequently, we simultaneously targeted inducer MACC1 and enforcer S100A4 within this axis of metastasis by combining clinically established drugs and generated efficient restriction of cancer cell motility and metastasis formation." (PMID 36008464, 2022). "We next tested whether the S100A4 protein was secreted from the cells by performing a human S100A4 ELISA with conditioned medium (CM) of cancer cells." (PMID 33549040, 2021). "S100A4 plays crucial roles in promotion of cancer malignancy and mitochondrial metabolism." (PMID 34145030, 2021). "In particular, S100A4 may serve as a target of therapies to prevent, control, or ablate cancer metastasis." (PMID 34124754, 2021). "Using conditioned medium from TNBC cells stimulated with FGF2, we have also ascertained that the paracrine activation of the S100A4/RAGE pathway triggers angiogenic effects in vascular endothelial cells (HUVECs) and promotes the migration of cancer-associated fibroblasts (CAFs)." (PMID 33946884, 2021). "In many types of cancers, S100A4 expression is correlated with a poor prognosis." (PMID 33994540, 2021). "S100A4 expression is a marker for malignancy in several cancer types, including CRC." (PMID 35008201, 2021). "Moreover, the expression of S100A4 can be boosted by diverse stimuli, including growth factors, cytokines, chemokines, and hypoxia in diverse types of cancers." (PMID 33946884, 2021). "Takenaga and Kozlova demonstrated that contrary to what occurs in other cell types, as cancer and immune cells, S100A4 was an inhibitor of WM astrocytes motility since its silencing promoted their migration and the expression of the metalloproteinase (MMP)-9 and metallothionein-1." (PMID 33918416, 2021). "S100A4 has been implicated in metastasis of cancer cells by interacting with non-muscle myosin IIA, IIB, and tropomyosin, thereby indirectly regulating migration." (PMID 32825277, 2020). "Furthermore, the EF hand Ca2+-binding protein, S100A4, has been shown to translocate from the nucleus to the plasma membrane in response to an increase in cytosolic Ca2+ in migrating cancer cells." (PMID 32825277, 2020). "S100A4 upregulated E-cadherin that was regulated by NF-κB/Snail and led to cancer metastasis." (PMID 32443845, 2020). "Activation of RAGE by S100A4, S100A7, S100A8, S100A9, S100A14, S100B, and S100P was associated with upregulation of NF-κB that induced progression of different types of cancer including pancreatic, melanoma, breast, prostate, colon, neuroblastoma, and esophageal." (PMID 32443845, 2020). "In many cancer cells, S100A4 is required for TGF-β1 effects on cell migration and invasion." (PMID 32619136, 2020). "S100A4 is a calcium-binding protein that has been shown to promote cancer progression and metastasis, enhance the motility of macrophages, neutrophils and leukocytes, and promote these inflammatory cells’ recruitment and chemotaxis to regulate inflammation and immune functions." (PMID 32619136, 2020). "S100A4 was first identified to correlate with cancer metastasis in 1989, followed by the finding that high S100A4 transfection could strengthen the tumorigenic potential and metastatic phenotype in vivo." (PMID 32154176, 2020). "Recent findings suggest that S100A4, a protein involved in communication between stromal cells and cancer cells, could be more involved than previously expected in cancer invasiveness." (PMID 32290283, 2020). "In addition, higher S100A4 expression was observed in various cancer types compared to MYLK, BDNF, and PCOLCE2." (PMID 31581665, 2019). "In this study, we investigated the importance of embigin and S100A4 in cancer progression." (PMID 30041429, 2018). "Accordingly, we first evaluated the effect of the S100A4-embigin axis on cancer cell migration." (PMID 30041429, 2018).
cancer (continued). "Consequently, S100A4 and Rhotekin are most likely to contribute to the conferring of invasive phenotypes of cancer cells." (PMID 30037057, 2018). "We supposed that the downregulation of miR-3189-3p might attenuate/counteract the inhibitory effect of S100A4 knockdown on the malignancy of cancer cells." (PMID 29342841, 2018). "RNAi was used to knock down S100A4 to study its effects on the properties of cancer cells." (PMID 29342841, 2018). "We were intrigued by the previous observation of high serum and tissue levels of S100A4 in cancer and chronic inflammation, and we thus hypothesized that exogenous S100A4 might support MDSC accumulation under inflammatory conditions." (PMID 29556233, 2018). "The results indicated that the reduced miR-3189-3p expression could attenuate/counteract the inhibitory effects of S100A4 knockdown on the malignancy of cancer cells, while miR-3189-3p mimics enhanced the effects." (PMID 29342841, 2018). "However, further researches are needed to manifest the exact function of S100A4 in various cancer stem cells." (PMID 30045697, 2018). "The finding that S100A4 is critical for MDSC survival in inflammatory environments might have important implications for the clinical treatment of cancer or inflammation-related diseases." (PMID 29556233, 2018). "S100A4 plays an important role in the invasion and metastasis of human malignant tumors." (PMID 29069865, 2017). "S100A4 has been shown to serve as a biomarker and a therapeutic target for cancer." (PMID 29069865, 2017). "This confirmatory analysis suggests that epigenetic silencing of miR-520c-3p is an important mechanism during cancer progression and could be one of the reasons for S100A4 upregulation in CRC cell lines." (PMID 28423501, 2017). "S100A4 is a well-known regulator of the growth and metastasis of human cancers." (PMID 28209128, 2017). "Furthermore, the role and mechanism of S100A4 in different types of cancers have been regulated by different signaling pathways and proteins." (PMID 29069865, 2017). "S100A4 has different biological functions in the normal state and in human malignant diseases including the enhancement of cell proliferation, angiogenesis, and cancer metastasis and immune evasion." (PMID 29069865, 2017). "S100A4 is not only expressed in normal cells, but also in various types of cancer cells." (PMID 29069865, 2017). "siRNA and promoter analysis showed that S100A4 is the first target of NFAT5 in cancer." (PMID 29069865, 2017). "Detection of S100A4 expression becomes a promising candidate biomarker in cancer early diagnosis and prediction of cancer metastasis and therefore, S100A4 may be a therapeutic target." (PMID 29069865, 2017). "S100A4 is active in the leading edge of migrating cancer cells." (PMID 28615627, 2017). "It is well established that S100A4 overexpression contributes to several hallmarks of cancer." (PMID 27127879, 2016). "In particular, S100A4, S100A6, S100A7 and S100A10 have been found to be overexpressed in some cancer types, and could be associated with aggressive cancer phenotype." (PMID 27008379, 2016). "The reduction in S100A4 protein levels also altered the cellular matrix remodeling genes, like MMPs and tissue inhibitors of metalloproteinases (TIMPs), responsible for the invasion of cancer cells into surrounding tissues." (PMID 27331819, 2016). "Additionally to cellular invasion, increased angiogenesis has been found in S100A4-related cancer, when extracellular S100A4 binds to the endothelial plasminogen co-receptor annexin 2 and plasminogen itself." (PMID 27331819, 2016). "Multiple strategies have been proposed to block S100A4 function in cancer." (PMID 27127879, 2016). "S100A4, a member of the S100 family, could modulate invasion, metastasis, apoptosis, and differentiation of various malignant tumors through different mechanisms." (PMID 27679610, 2016).